IGSF9B (immunoglobulin superfamily member 9B)
Description:
Transmembrane protein which is abundantly expressed in interneurons, where it may regulate inhibitory synapse development (By similarity). May mediate homophilic cell adhesion (By similarity). Is involved in the organization and maintenance of axon initial segment (AIS) architecture, likely cooperating with PRICKLE2 to regulate ANK3/ANKG localization to AIS (By similarity).
Synonyms: KIAA1030; LINC00947; LOC283174; MIR4697HG
Tractability: Antibody: UniProt places it where antibodies can reach, with medium confidence; UniProt predicts a signal peptide or a membrane-spanning region; its Gene Ontology location is reachable by antibodies, with medium confidence.
Gene: Protein-coding gene on chromosome 11 (133,896,438 to 133,956,968, reverse strand). Ensembl gene ENSG00000080854.
Subcellular location: Postsynaptic cell membrane; Postsynaptic density; Cell projection, axon
Subcellular location (Human Protein Atlas): Cell Junctions; Golgi apparatus
Gene Ontology:
Cellular component: neuron projection; postsynaptic density; postsynaptic membrane; axon; GABA-ergic synapse
Genetic constraint (gnomAD): Loss-of-function variants: 48 observed, 126.47 expected, observed/expected ratio (o/e) 0.38, 90% interval 0.3 to 0.48. The upper end of that interval is the gene's LOEUF score, 0.48, which puts it in group 2 of 6, group 1 being the genes least tolerant of losing a copy. Missense variants: 1,699 observed, 1,917.6 expected, observed/expected ratio (o/e) 0.89, 90% interval 0.85 to 0.92. Synonymous variants: 903 observed, 807.15 expected, observed/expected ratio (o/e) 1.12, 90% interval 1.06 to 1.18.
Homologues: Orthologues: chimpanzee IGSF9B (99% identical), macaque IGSF9B (98% identical), rabbit IGSF9B (97% identical), dog IGSF9B (96% identical), mouse Igsf9b (96% identical), pig IGSF9B (96% identical), guinea pig IGSF9B (91% identical), rat Igsf9b (90% identical), tropical clawed frog igsf9b (72% identical), zebrafish igsf9bb (65% identical). Paralogues in human: IGSF9 (34% identical), HMCN2 (15% identical), SDK2 (15% identical), ROBO1 (15% identical), SDK1 (15% identical), ROBO2 (15% identical), IGSF10 (14% identical), ROBO3 (14% identical), DCC (14% identical), MXRA5 (14% identical), NEO1 (13% identical), IGDCC4 (12% identical), and 24 more.
Diseases named in the same sentence as IGSF9B in open-access papers:
IGSF9B is named in the same sentence as 14 diseases in open-access papers, as found by Europe PMC text mining. Sharing a sentence is not in itself a finding about the gene and the disease. The quoted sentences say what the papers report.
major depression (3 papers, 2018 to 2025). "In genome-wide association analyses, the IGSF9B locus was found to be linked to the etiology of schizophrenia and major depression, as well as to Parkinson’s disease, multiple sclerosis, and migraine." (PMID 41105221, 2025). "Immunoglobulin superfamily member 9b (IgSF9b) is a cell adhesion protein that has been linked to the etiology of several neuropsychiatric disorders, most notably schizophrenia and major depression." (PMID 41105221, 2025). "The anxiolytic effects of IgSF9b deletion in Nlgn2 KO mice are intriguing in light of previous studies showing that variants in IgSF9b are associated with major depression and the negative (mainly affective) symptoms of schizophrenia." (PMID 30573727, 2018). "Variants in IgSF9b are associated with major depression and the negative symptoms of schizophrenia, indicating that IgSF9b may regulate affect in human patients." (PMID 30573727, 2018).
schizophrenia (3 papers, 2021 to 2025). A major psychotic disorder characterized by abnormalities in the perception or expression of reality. "This region contributes to a wide range of aspects in memory formation and spatial context recognition, and it is possible that loss of function of IgSF9b may lead to disruptions in related cognitive functions, including those observed in patients with schizophrenia." (PMID 41105221, 2025). "One CpG site (cg08170519) annotated to IGSF9B showed strong evidence of colocalization (PPH4 = .98), suggesting a single shared variant affecting the two traits (i.e. LVV‐associated DNAm and schizophrenia)." (PMID 37469193, 2024). "In the present study, we provide a neuroanatomical characterization of the expression pattern and synaptic localization of the cell adhesion protein IgSF9b, which has been proposed to contribute to the etiology of schizophrenia and other brain disorders through its role at GABAergic synapses." (PMID 41105221, 2025). "Interestingly, promotion of IGSF9B for inhibitory synapses development is coupled with NLGN2, loss of function variants of which were found in autism and schizophrenia patients." (PMID 33795679, 2021). "One CpG site showed significant colocalization: cg08170519 is located in IGSF9B, a gene involved in GABA neurotransmission/inhibitory synapse development and Vitamin D receptor pathway processes, which have been repeatedly implicated in schizophrenia (Cui, McGrath, Burne, & Eyles, 2021)." (PMID 37469193, 2024).
Anxiety (2 papers, 2018 to 2025). Intense feelings of nervousness, tension, or panic often arise in response to interpersonal stresses. "Here we study the role of IgSF9b, an adhesion protein that has been associated with affective disorders, in the amygdala anxiety circuitry." (PMID 30573727, 2018). "Together, our data indicate that deletion of IgSF9b in the CeM results in an increase in inhibitory synapse function, which may underlie its behavioral consequences in the anxiety circuitry." (PMID 30573727, 2018). "At present, both the function of these beta oscillations in anxiety processing and the mechanisms that underlie their modulation by Nlgn2 and IgSF9b remain unknown." (PMID 30573727, 2018). "Here the authors show that deletion of IgSF9b regulates anxiety-like behaviour in mice by increasing inhibitory synaptic transmission in the centromedial amygdala." (PMID 30573727, 2018). "Given that the normalization of anxiety-related behaviors can be mimicked by local shRNA-mediated knockdown of IgSF9b in the CeM of Nlgn2 KO mice, it is likely to occur through a local mechanism within the CeM." (PMID 30573727, 2018). "Together, our data provide the first description of IgSF9b function in vivo and uncover a novel role for IgSF9b in anxiety-related behavior and amygdala inhibitory synapses." (PMID 30573727, 2018). "Combined evidence from our cFos analysis, retrograde tracing experiments, and in vivo electrophysiology indicates that IgSF9b deletion normalizes anxiety-related output specifically in the CeM of Nlgn2 x IgSF9b double KO mice." (PMID 30573727, 2018). "In the present study we sought to elucidate the role of the cell adhesion molecule IgSF9b and its interactions with Nlgn2 in amygdala circuits, synapses, and behaviors related to anxiety processing." (PMID 30573727, 2018). "We show that IgSF9b regulates anxiety-like behaviors in Nlgn2 KO mice and that IgSF9b and Nlgn2 exert differential effects on distinct components of the amygdala inhibitory circuitry." (PMID 30573727, 2018). "Second, do IgSF9b and/or Nlgn2 act at specific inhibitory synapses within the anxiety circuitry and thus offer synapse-specific targets for interventions?" (PMID 30573727, 2018). "Altogether, our findings are consistent with a model in which IgSF9b deletion normalizes anxiety-related behaviors and neuronal activity by increasing inhibition onto CeM output neurons and hence counteracting the anxiety-related overactivation of the CeM." (PMID 30573727, 2018). "We show that deletion of IgSF9b has anxiolytic consequences and normalizes the prominent anxiety phenotype observed in Nlgn2 KO mice." (PMID 30573727, 2018). "Further experiments will be essential to fully understand how Nlgn2 and IgSF9b regulate beta oscillations in the CeM and how this contributes to the generation and normalization of pathological anxiety processing." (PMID 30573727, 2018). "Given that IgSF9b is highly expressed in the CeM, these data confirm that IgSF9b modulates anxiety-related behaviors through a CeM-specific mechanism, and indicates that targeting inhibitory transmission in the CeM can ameliorate anxiety-related behaviors." (PMID 30573727, 2018). "However, the effectiveness of the local deletion of IgSF9b in CeM in mimicking the double KO phenotype indicates that any such upstream alterations cannot be required for the normalization of anxiety-related behaviors by IgSF9b deletion." (PMID 30573727, 2018). "In the present study, we investigated the role of synaptic inhibition in anxiety by addressing two key questions: First, does IgSF9b regulate anxiety-related behavior and neural processing in the anxiety circuitry of WT and/or pathologically anxious Nlgn2 KO mice?" (PMID 30573727, 2018). "Deletion of IgSF9b increased the number of VIAAT puncta in Nlgn2 KO mice (red and blue striped bars), an effect that may underlie the rescue of anxiety-related behavior in Nlgn2 KO mice following local deletion of IgSF9b in the CeM." (PMID 30573727, 2018).
Anxiety (continued). "To address the role of IgSF9b in anxiety processing, we first tested whether IgSF9b deletion would alter anxiety-related behaviors and/or modulate the anxiety phenotype observed in Nlgn2 KO mice." (PMID 30573727, 2018). "To this end, we investigated the consequences of IgSF9b deletion and IgSF9b x Nlgn2 double deletion on anxiety-related behavior and circuits, as well as on inhibitory synapses in the amygdala, a brain region that plays a central role in the processing of anxiety information." (PMID 30573727, 2018). "Together, these data indicate that Nlgn2 and IgSF9b deletion affect distinct targets within the amygdala: While Nlgn2 regulates anxiety-induced activation of projection neurons in BA, IgSF9b may normalize the CeM anxiogenic output by local mechanism within the CeM." (PMID 30573727, 2018). "Finally, we investigated the consequences of IgSF9b deletion on synaptic inhibition in the BA, in order to determine whether the differential effects of IgSF9b deletion on anxiety-related neuronal activation in the BA and the CeM are also reflected at the synaptic level." (PMID 30573727, 2018). "We show that deletion of IgSF9b normalizes anxiety-related behaviors and neural processing in mice lacking the synapse organizer Neuroligin-2 (Nlgn2), which was proposed to complex with IgSF9b." (PMID 30573727, 2018). "Given that IgSF9b and Nlgn2 function at distinct synapses and do not appear to interact in a cell-autonomous manner, at least in the amygdala, how does deletion of IgSF9b normalize the prominent anxiety phenotype observed in Nlgn2 KO mice?" (PMID 30573727, 2018). "Interestingly, anxiety levels appeared to be exacerbated in Nlgn2 KO but not in WT mice over the observed 6-week time period, even in mice that had not undergone surgery, and this effect was completely reversed by local reduction of IgSF9b." (PMID 30573727, 2018). "While it was originally proposed that IgSF9b links to Nlgn2 via S-SCAM as a bridging molecule and thereby recruits gephyrin and other GABAergic synapse components, we subsequently found that, at least within the amygdala anxiety circuitry, IgSF9b and Nlgn2 do not appear to act at the same synapses." (PMID 41105221, 2025).
breast carcinoma (1 paper, 2016). "Moreover, we present evidence that a three-gene set—WNT5A, CNGA2, and IGSF9B—can be used as a signature associated with shorter survival in breast cancer patients." (PMID 28097125, 2016). "Furthermore, we present evidence that a three-gene set—WNT5A, CNGA2 and IGSF9B—was associated with shorter survival in breast cancer patients." (PMID 28097125, 2016).
epilepsy (1 paper, 2024). A brain disorder characterized by episodes of abnormally increased neuronal discharge resulting in transient episodes of sensory or motor neurological dysfunction, or psychic dysfunction. "Conversely, an increase in the expression levels of SLIT and NTRK-like family, member 1 (Slitrk1), TYRO3 protein tyrosine kinase 3 (Tyro3), epilepsy, progressive myoclonic epilepsy, type 2 gene alpha (Epm2a), fucosyl-transferase 9 (Fut9), immunoglobulin superfamily, member 9B (Igsf9b) was observed." (PMID 38535448, 2024).
migraine (1 paper, 2020). "Two SNPs, rs561561 (IGSF9B) and rs4910165 (MRVI1), were both found to be selective for migraine characterized by nausea/vomiting (pcor = 0.010 and 0.006, respectively) in the combined full and probable migraineurs." (PMID 33643179, 2020).
Parkinson disease (1 paper, 2025). A progressive degenerative disorder of the central nervous system characterized by loss of dopamine producing neurons in the substantia nigra and the presence of Lewy bodies in the substantia nigra and locus coeruleus. "Interestingly, high expression of IgSF9b was also observed in brain regions related to motor behaviors, including the globus pallidus, substantia nigra, and cerebellum, which may provide an explanation for its putative association with Parkinson’s disease." (PMID 41105221, 2025).
psychiatric disorder (3 papers, 2018 to 2025). A disorder characterized by behavioral and/or psychological abnormalities, often accompanied by physical symptoms. "Here, because Igsf9 family proteins are associated with psychiatric diseases and seizures, we studied the physiological interaction between Prickle2 and Igsf9b." (PMID 32641624, 2020). "IgSF9b is a synaptic adhesion protein that has been linked to psychiatric disorders." (PMID 30573727, 2018). "Future detailed analyses of the molecular, cellular and functional consequences of IgSF9b deletion at each of these sites will be essential to determine its contribution to human psychiatric disorders." (PMID 41105221, 2025).
IGSF9B also shares sentences with these, for which no sentence is quoted: tumor (2 papers); autism (1); brain disorder (1); myoclonic epilepsy (1); ovarian carcinoma (1); pancreatic cancer (1).